ZBTB46 (zinc finger and BTB domain containing 46)
Description:
Transcription regulator that mediates differentiation of conventional and non-conventional dendritic cells, and which is involved in tolerance to gut microbiota. Together with RORgammaT (RORC), specifically expressed in type 3 innate lymphoid cells (ILC3s) that are required for tolerance to gut microbiota, to mediate differentiation of peripherally-induced regulatory T-cells (pTreg), which suppress inflammatory responses to commensal microorganisms. Functions as a transcription corepressor for PRDM1.
Synonyms: BTBD4; ZNF340; FLJ13502; RINZF; BZEL; dJ583P15.7; dJ583P15.8
Tractability: PROTAC: UniProt records ubiquitination sites on it; ubiquitination databases record sites on it.
Gene: Protein-coding gene on chromosome 20 (63,743,668 to 63,832,455, reverse strand). Ensembl gene ENSG00000130584.
Subcellular location: Nucleus; Chromosome
Subcellular location (Human Protein Atlas): Nucleoplasm
Gene Ontology:
Molecular function: DNA-binding transcription factor activity, RNA polymerase II-specific; DNA-binding transcription repressor activity, RNA polymerase II-specific; RNA polymerase II transcription regulatory region sequence-specific DNA binding; transcription cis-regulatory region binding; transcription coregulator activity
Biological process: regulation of transcription by RNA polymerase II; negative regulation of transcription by RNA polymerase II; regulatory T cell differentiation; tolerance induction in gut-associated lymphoid tissue
Cellular component: chromatin; chromosome; nucleus
Genetic constraint (gnomAD): Loss-of-function variants: 9 observed, 41.44 expected, observed/expected ratio (o/e) 0.22, 90% interval 0.13 to 0.38. The upper end of that interval is the gene's LOEUF score, 0.38, which puts it in group 1 of 6, group 1 being the genes least tolerant of losing a copy. Missense variants: 651 observed, 829.22 expected, observed/expected ratio (o/e) 0.79, 90% interval 0.74 to 0.84. Synonymous variants: 409 observed, 378.12 expected, observed/expected ratio (o/e) 1.08, 90% interval 1 to 1.17.
Homologues: Orthologues: chimpanzee ZBTB46 (99% identical), macaque ZBTB46 (99% identical), guinea pig ZBTB46 (91% identical), mouse Zbtb46 (91% identical), rat Zbtb46 (91% identical), dog ZBTB46 (90% identical), pig ZBTB46 (86% identical), tropical clawed frog zbtb46 (69% identical), zebrafish zbtb46 (63% identical). Paralogues in human: BCL6 (21% identical), ZBTB21 (19% identical), BCL6B (18% identical), ZBTB49 (18% identical), ZBTB3 (16% identical), ZBTB14 (15% identical), ZBTB33 (15% identical), NACC2 (15% identical), ZBTB12 (14% identical), ZBTB26 (14% identical), NACC1 (14% identical), ZBTB7B (14% identical), and 16 more.
Diseases named in the same sentence as ZBTB46 in open-access papers:
ZBTB46 is named in the same sentence as 21 diseases in open-access papers, as found by Europe PMC text mining. Sharing a sentence is not in itself a finding about the gene and the disease. The quoted sentences say what the papers report.
atherosclerosis (5 papers, 2016 to 2023). A disease characterized by the build-up of fatty material and calcium deposition in the arterial wall resulting in partial or complete occlusion of the arterial lumen. "This led to the finding that rs7648433, located in ZBTB46 gene, was associated with this phenotype and it has been implicated in mechanisms such as shear stress and atherosclerosis in other studies." (PMID 34300314, 2021).
prostate carcinoma (4 papers, 2019 to 2021). A carcinoma that arises from epithelial cells of the prostate gland. "We identified consensus molecular pathways in prostate cancer cells that are modulated by the NGF–CHRM4-upregulated neuroendocrine-like phenotype via activation of the ZBTB46 transcription factor." (PMID 33398073, 2021). "Here, the authors discover that NGF, upregulated by transcription factor ZBTB46 in prostate cancer exposed to androgen therapy, promotes neuroendocrine differentiation." (PMID 33398073, 2021). "Thus, we discovered a mechanism of prostate cancer lineage plasticity that provides an effective prediction strategy utilizing gene expression-based biomarkers for NEPC development through the association of activated ZBTB46 and accumulated NGF via stimulation of the CHRM4–AKT–MYCN pathway." (PMID 33398073, 2021). "We hypothesized that ZBTB46 upregulates NGF expression in prostate cancer cells by acting as a transcriptional activator and binding to a ZBTB46-binding element (ZBE) in the NGF regulatory sequence." (PMID 33398073, 2021). "We also found that NGF overexpression or NGF-knockdown in prostate cancer cells, respectively, increased or decreased ZBTB46 expression, suggesting that activated NGF may play a positive feedback role in regulating ZBTB46." (PMID 33398073, 2021). "To investigate whether NGF stimulation is associated with ZBTB46 after ADT, we examined prostate cancer samples consisting of tissue specimens collected from 18 prostate cancer patients before and after ADT at Taipei Medical University-Wan Fang Hospital (Taipei, Taiwan)." (PMID 33398073, 2021). "Our earlier study demonstrated that ADT activates ZBTB46, a prostatic tumor promoter, which promotes the epithelial–mesenchymal transition through transcriptional regulation of SNAI123 and is associated with neuroendocrine differentiation and tumor recurrence in prostate cancer after ADT24." (PMID 33398073, 2021). "To identify the regulatory mechanisms between ZBTB46-NGF signaling and NEPC differentiation, we examined ZBTB46 and NGF expressions in gene signatures of NEPC in TCGA prostate cancer dataset by a GSEA." (PMID 33398073, 2021). "The mean expression correlation was analyzed in prostate cancer datasets, which showed that CHRM4 was positively correlated with NGF, ZBTB46, and neuroendocrine marker expressions and inversely correlated with androgen-responsive gene expressions." (PMID 33398073, 2021). "To study the regulatory mechanisms involved in ZBTB46 upregulation during NEPC development, we examined relationships between ZBTB46 and activation of signatures of NEPC-responsive genes in The Cancer Genome Atlas (TCGA) prostate cancer dataset." (PMID 33398073, 2021).
influenza (2 papers, 2021). An acute viral infection of the respiratory tract, occurring in isolated cases, in epidemics, or in pandemics; it is caused by serologically different strains of viruses (influenzaviruses) designated A, B, and C, has a 3-day incubation period, and usually lasts for 3 to 10 days. "Our study showed that compared with the TT genotype, the TC + CC genotype of ZBTB46 rs2281929 was significantly associated with better responsiveness to influenza vaccination in both qualitative and quantitative analyses." (PMID 34276655, 2021). "Our study identified two novel candidate missense variants, ZBTB46 rs2281929 and IQGAP2 rs2455230, were associated with the immune response to influenza vaccination among the Chinese population." (PMID 34276655, 2021). "More recently, when genome-wide association studies (GWAS) were employed, two novel candidate missense variants, ZBTB46 rs2281929 and IQGAP2 rs2455230, were found to be associated with the immune response to influenza vaccination among the Chinese population." (PMID 34696202, 2021). "Finally, we observed that ZBTB46 rs2281929 and IQGAP2 rs2455230 are associated with the antibody response to influenza vaccine." (PMID 34276655, 2021). "Finally, two SNPs including ZBTB46 rs2281929 and IQGAP2 rs2455230 were found to be significantly correlated with the serological response to influenza vaccine." (PMID 34276655, 2021).
COVID-19 (1 paper, 2025). A disease caused by infection with severe acute respiratory syndrome coronavirus 2. "By 6 weeks post-inclusion (T2), COVID-19 hypermethylation of genes with lowest p-value included NXN, FMNL2, ZBTB46, SLC35F3, and SHQ1, and the hypomethylated genes included ELMO1, XBP1, GRIK1, TNFAIP8, and SH3BP5." (PMID 41227320, 2025).
leukaemia (1 paper, 2025). "There is no clear evidence linking the zinc finger domain of ZBTB46 to leukaemia." (PMID 39887881, 2025).
lung carcinoma (1 paper, 2025). "Further functional characterization may establish ZBTB46 as a promising diagnostic and therapeutic target for lung cancer." (PMID 40780118, 2025). "In the present study, we characterized the circRNA expression landscapes of lung cancer and paracancerous tissues to elucidate the functional roles and underlying mechanisms of ZBTB46 in lung cancer pathogenesis, thereby providing novel therapeutic strategies for this disease." (PMID 40780118, 2025). "Moreover, ZBTB46 expression was significantly associated with clinicopathological parameters (T/N stage, gender, smoking status/pack-years), indicating its involvement in lung cancer pathogenesis." (PMID 40780118, 2025). "Depending on the expression level of ZBTB46, lung cancer patients were divided into two groups: the high-expression group and the low-expression group." (PMID 40780118, 2025). "ZBTB46 mRNA and protein expression were reduced in human lung cancer tissue compared to normal tissue." (PMID 40780118, 2025). "While ZBTB46 promotes tumorigenesis in neuroendocrine prostate cancer, its role in lung cancer remains underexplored." (PMID 40780118, 2025). "A relationship between Immune checkpoints and ZBTB46 was examined considering ZBTB46′s potential tumor suppressor role in lung cancer." (PMID 40780118, 2025). "CPTAC and HPA were used to explore the protein expression of ZBTB46 in lung cancer following mRNA analysis." (PMID 40780118, 2025). "In conclusion, the authors found that patients with lung cancer had significantly low levels of ZBTB46 protein expression." (PMID 40780118, 2025). "Despite its emerging role as a key regulator in immunity, the role of ZBTB46 in lung cancer progression, particularly regarding immune infiltration and immune checkpoint pathways, remains uncharacterized." (PMID 40780118, 2025). "Collectively, the present findings identify the hsa_circ_0002872/hsa-miR-29b-1–5p/ZBTB46 axis as a novel regulator of lung cancer progression, with ZBTB46 serving as a potential prognostic marker and therapeutic target." (PMID 40780118, 2025). "Lung cancer tissues expressed low levels of ZBTB46 proteins, as determined by HPA, compared with normal tissues." (PMID 40780118, 2025). "ZBTB46 is a key molecule that inhibits lung cancer progression and is considered a significant prognostic marker for lung cancer patients." (PMID 40780118, 2025). "Lung cancer tissues expressed low levels of ZBTB46 protein, whereas they were medium levels in normal lung tissues." (PMID 40780118, 2025). "This study intends to investigate circRNA expression and the role of ZBTB46 in predicting and treating lung cancer." (PMID 40780118, 2025). "Bioinformatics approaches were then applied to the TCGA database and multiple online analysis platforms, compared with adjacent normal tissues, lung cancer tissues exhibited lower expression levels of ZBTB46 mRNA and protein." (PMID 40780118, 2025). "First, it represents a preliminary investigation into ZBTB46′s role in lung cancer, requiring additional experiments to validate predicted molecular mechanisms." (PMID 40780118, 2025). "•ZBTB46 expression in lung cancer correlates with prognosis, immune cell infiltration, and immune checkpoints." (PMID 40780118, 2025). "In lung cancer tissue, ZBTB46, like hsa_circ_0002872, has a lower expression level than in normal lung tissue." (PMID 40780118, 2025). "Therefore, based on ceRNA theory, the authors selected hsa-miR-29b-1–5p, which is highly expressed in lung cancer, and predicted the most potential downstream circRNA axis: hsa_circ_0002872/hsa-miR-29b-1–5p/ZBTB46." (PMID 40780118, 2025). "In conclusion, hsa_circ_0002872/hsa-miR-29b-1–5p/ZBTB46 is an axis that may influence lung cancer progression." (PMID 40780118, 2025). "ZBTB46 expression in lung cancer tissue was compared to normal tissue." (PMID 40780118, 2025). "•hsa_circ_0002872/hsa-miR-29b-1-5p/ZBTB46 axis predicted to affect lung cancer progression." (PMID 40780118, 2025).
lung carcinoma (continued). "ZBTB46 was identified as a novel lung cancer biomarker in this study." (PMID 40780118, 2025). "hsa_circ_0002872/hsa-miR-29b-1–5p/ZBTB46 represents an axis that may influence lung cancer progression, with the molecule ZBTB46 potentially inhibiting lung cancer progression and serving as a useful prognostic indicator." (PMID 40780118, 2025). "•Study suggests ZBTB46 as a potential biomarker and target for lung cancer immunotherapy." (PMID 40780118, 2025). "Thus, elucidating the therapeutic and prognostic relevance of ZBTB46 in lung cancer is imperative." (PMID 40780118, 2025). "It was observed that ZBTB46 expression correlated significantly positively with all types of immune cells analyzed, including B-cells, CD8+ T-cells, CD4+ T-cells, macrophages, neutrophils, and dendritic cells in lung cancer." (PMID 40780118, 2025). "Notably, ZBTB46 has not been previously investigated in lung cancer." (PMID 40780118, 2025).
multiple sclerosis (1 paper, 2017). A progressive autoimmune disorder affecting the central nervous system resulting in demyelination. "A genetic polymorphism in ZBTB46 (rs6062314) was associated with multiple sclerosis, with the identified SNP located 7298 bp from the ZBTB46 CpG site associated in our study." (PMID 29311901, 2017).
skin cancer (1 paper, 2023). "Our results show that a marked correlation between the CD103+DC signature (IRF8, FMS‐like tyrosine kinase 3 ligand, CLEC9A, CLNK, XCR1, BATF3, and ZBTB46) and chemokines C‐X‐C motif chemokine ligand 9, CXCL10, and CD8A in a mouse model with DMBA/TPA‐induced skin cancer." (PMID 36891351, 2023).
tumor (11 papers, 2018 to 2025). "As a transcriptional repressor, ZBTB46 regulates tumor angiogenesis and modulates vascular endothelial cell function." (PMID 40780118, 2025). "Third, mechanistic evidence linking ZBTB46 to immune infiltration and tumor-immune interactions remains limited." (PMID 40780118, 2025). "We next transferred Zbtb46-DTR bone marrow cells into irradiated KP or KP7 mice followed by tumor induction and DT treatment for more specific depletion of DCs." (PMID 33257678, 2020). "Additionally, ZBTB46 remodels immune cell composition and enhances anti-tumor immune effector functions in the tumor microenvironment, thereby influencing cancer prognosis." (PMID 40780118, 2025). "It appears that ZBTB46 can inhibit lung tumor development via tumor immune escape." (PMID 40780118, 2025). "ZBTB46 plays a critical role in tumor immunity by governing the ontogeny and functional integrity of conventional Dendritic Cells-2 (cDC2), thus regulating antigen presentation and T-cell immunity within the tumor microenvironment." (PMID 40780118, 2025). "Overall, ZBTB46 may alter immune responses in the tumor microenvironment through its effect on immune cells." (PMID 40780118, 2025). "A study with mice showed that prostaglandin PGE2 synthesized in lymphoma cancer cells results in inhibition of ZBTB46 (zinc finger and BTB Domain Containing 46) factor expression (only expressed in cDC), thus preventing differentiation to cDC and favoring tumor expansion." (PMID 34199169, 2021). "For example, treatment of tumor-bearing mice with NS-398 (COX-2 inhibitor), to reduce prostaglandin synthesis of tumor cells, can enhance the transcription factor Zbtb46, induce cDC lineage maturation, and enhance the activity of DCs." (PMID 36244976, 2022). "We found GMPs, MDPs, and CDPs from tumor-bearing mice failed to upregulate proteins indicative of the cDC program (e.g., Irf8, Zbtb46, Cd209a, Spib, Batf3, and Bcl11a)." (PMID 29593283, 2018). "Additionally, this strategy increases ZBTB46 expression in endothelial cells at tumor sites via NO, further supporting vessel normalization and T‐cell infiltration without promoting tumor growth." (PMID 40917034, 2025).
cancer (2 papers, 2022 to 2025). A tumor composed of atypical neoplastic, often pleomorphic cells that invade other tissues. "Hypermethylation and reduction in TSG function of SRGAP2C (Slit-Robo Rho GTPase-activating protein 2C) and ZBTB46 (zinc finger and born-to-bind domain containing 46) were associated with tumorigenesis and cancer metastasis." (PMID 35629083, 2022). "We found that age was a significant predictor in obese cancer patients, both alone (p = 0.003) and interacting with hypomethylated DMRs of ZBTB46, a tumor suppressor gene (p = 0.008)." (PMID 35629083, 2022). "Although located on an intron, the DMR affecting ZBTB46 showed a 36% reduction in methylation between obese and non-obese cancer groups, and GR analysis showed significant interaction with age (p = 0.024)." (PMID 35629083, 2022).
infection (1 paper, 2022). The state of being infected such as from the introduction of a foreign agent such as serum, vaccine, antigenic substance or organism. "We also identified by scRNAseq, a unique Bcl3-dependent hybrid subpopulation of Zbtb46+ DCs co-expressing the monocyte/macrophage transcription factor Lysozyme M. This subpopulation exhibited Bcl3-dependent expansion after infection." (PMID 36318581, 2022). "In the present study, we show that mice lacking the NF-κB regulator Bcl3 in cells expressing Zbtb46, a selective marker of cDCs, succumb 3–5 weeks after i.p. infection with T. gondii." (PMID 36318581, 2022).
ZBTB46 also shares sentences with these, for which no sentence is quoted: Obesity (2 papers); asthma (1); celiac disease (1); colon cancer (1); osteoporosis (1); pancreatic cancer (1); prion disease (1); prostatic tumor (1); rheumatoid arthritis (1); Sepsis (1).